STX6 (syntaxin 6)
Description:
SNARE promoting movement of transport vesicles to target membranes. Targets endosomes to the trans-Golgi network, and may therefore function in retrograde trafficking. Together with SNARE STX12, promotes movement of vesicles from endosomes to the cell membrane, and may therefore function in the endocytic recycling pathway.
Tractability: Antibody: its Gene Ontology location is reachable by antibodies, with high confidence; UniProt predicts a signal peptide or a membrane-spanning region. PROTAC: ubiquitination databases record sites on it; its protein half-life has been measured.
Gene: Protein-coding gene on chromosome 1 (180,972,712 to 181,023,121, reverse strand). Ensembl gene ENSG00000135823.
Subcellular location: Golgi apparatus membrane; Golgi apparatus, trans-Golgi network membrane; Recycling endosome membrane
Subcellular location (Human Protein Atlas): Golgi apparatus; Cytosol; Nucleoplasm
Pathways (Reactome):
Vesicle-mediated transport: Intra-Golgi traffic; Retrograde transport at the Trans-Golgi-Network
Gene Ontology:
Molecular function: protein binding; syntaxin binding; SNARE binding; SNAP receptor activity
Biological process: endocytic recycling; regulation of protein localization; retrograde transport, endosome to Golgi; vesicle fusion; Golgi vesicle transport; intracellular protein transport; synaptic vesicle to endosome fusion; vesicle-mediated transport
Cellular component: early endosome; Golgi apparatus; Golgi membrane; perinuclear region of cytoplasm; SNARE complex; trans-Golgi network; clathrin-coated vesicle; plasma membrane; recycling endosome; recycling endosome membrane; synaptic vesicle membrane; trans-Golgi network membrane; cytosol; membrane; vesicle
Genetic constraint (gnomAD): Loss-of-function variants: 12 observed, 23.27 expected, observed/expected ratio (o/e) 0.52, 90% interval 0.33 to 0.83. The upper end of that interval is the gene's LOEUF score, 0.83, which puts it in group 3 of 6, group 1 being the genes least tolerant of losing a copy. Missense variants: 167 observed, 209.57 expected, observed/expected ratio (o/e) 0.8, 90% interval 0.7 to 0.91. Synonymous variants: 81 observed, 78.86 expected, observed/expected ratio (o/e) 1.03, 90% interval 0.86 to 1.24.
Homologues: Orthologues: chimpanzee STX6 (100% identical), macaque STX6 (99% identical), guinea pig STX6 (96% identical), mouse Stx6 (95% identical), dog STX6 (92% identical), rat Stx6 (89% identical), pig STX6 (80% identical), zebrafish stx6 (76% identical), tropical clawed frog stx6 (75% identical), Drosophila melanogaster Syx6 (46% identical), Caenorhabditis elegans syx-6 (19% identical). Paralogues in human: STX10 (61% identical), STX8 (21% identical).
Diseases named in the same sentence as STX6 in open-access papers:
STX6 is named in the same sentence as 54 diseases in open-access papers, as found by Europe PMC text mining. Sharing a sentence is not in itself a finding about the gene and the disease. The quoted sentences say what the papers report.
prion disease (8 papers, 2022 to 2026). A transmissible disease that is caused by a protein that is able to induce abnormal folding of normal cellular proteins, leading to characteristic spongiform brain changes, which are associated with neuronal loss without an inflammatory response. "Complementary in vivo studies showed that syntaxin-6 influences early stages of prion disease in experimental mice, increasing transmission risk after inoculation with low prion doses." (PMID 41186731, 2025). "Variants in and around STX6 have also been associated with risk of the prion disease, specifically sporadic Creutzfeldt-Jakob disease, with a recent study showing that upregulation of both gene and protein expression of syntaxin-6 in the brain is associated with the disease risk." (PMID 40618089, 2025). "We hypothesised that syntaxin-6 confers risk of prion disease by modification of one of these key three stages: the establishment of disease, prion propagation or prion-induced toxicity." (PMID 41186731, 2025). "Variants in and around STX6 have also been associated with risk of the prion disease, specifically sporadic Creutzfeldt-Jakob disease, with a recent study showing that genetic upregulation of both gene and protein expression of syntaxin-6 in the brain is associated with the disease risk." (PMID 39975316, 2025). "A transmission study in Stx6−/−, Stx6+/ and Stx6+/+ mice challenged with two prion strains showed reduced syntaxin-6 expression is associated with a modest prolongation of prion disease incubation periods, supporting a pathological role of Stx6 expression in prion disease pathogenesis." (PMID 37996040, 2024). "It has been suggested that increased expression of Syntaxin-6 (Stx6) in the basal ganglia could raise the risk of prion disease, and Stx-6 deposits have been identified as a risk factor for a 4R-tauopathy and progressive supranuclear palsy." (PMID 35327482, 2022). "If syntaxin-6 is involved in these initial events more therapeutic promise may come from targeting syntaxin-6 prior to disease onset in at-risk individuals prior to initial seeding (applicable for inherited prion disease cases)." (PMID 37996040, 2024). "Genetically mediated increased expression of syntaxin-6, a SNARE protein involved in intracellular protein trafficking, is a proposed risk mechanism for progressive supranuclear palsy and sporadic prion disease." (PMID 42017988, 2026). "Increased expression of syntaxin-6, a SNARE protein involved in intracellular protein trafficking, is a proposed genetic risk mechanism for sporadic prion disease and progressive supranuclear palsy, as well as being implicated in Alzheimer’s disease." (PMID 41186731, 2025). "In conclusion, we identify syntaxin-6 as a modifier of early prion disease pathogenesis in vivo and demonstrate its role in regulating the trafficking and export of prions." (PMID 41186731, 2025). "To explore a role for Stx6 expression in prion disease pathogenesis, we conducted a classical prion transmission study in a newly developed mouse model which has a genetic reduction in Stx6 expression." (PMID 37996040, 2024). "For each of the 10–5, 10–6, 10–7, and 10–8 concentrations, the proportion of prion disease cases relative to the animals surviving to the end of the study (attack rate) was consistently lower in Stx6−/− mice relative to Stx6+/+ mice, suggesting that they were more resistant to disease development." (PMID 41186731, 2025). "This in vivo data is therefore in keeping with the hypothesis derived from GWAS discovery that increased STX6 expression promotes prion disease pathogenesis." (PMID 37996040, 2024). "Importantly however, prion transmission studies model a form of acquired prion disease, raising the possibility that syntaxin-6 plays a role across different aetiologies of prion disease and across species." (PMID 37996040, 2024).
prion disease (continued). "Finally, it is plausible the effect of modified syntaxin-6 function has more widespread implications for cellular function, which may indirectly affect all aspects of prion disease biology." (PMID 37996040, 2024). "The previous data would suggest a protective rather than deleterious effect of syntaxin-6 in prion disease." (PMID 39109999, 2024). "In this study, C57BL/6N female mice with genetic reduction of syntaxin-6 showed prolonged mouse prion disease incubation periods for both prion strains tested, however this does not appear to correlate directly with syntaxin-6 expression." (PMID 37996040, 2024).
progressive supranuclear palsy (7 papers, 2017 to 2026). A rare late-onset neurodegenerative disease characterized by supranuclear gaze palsy, postural instability, progressive rigidity, and mild dementia. "Variants at the syntaxin-6 (STX6) locus have been identified by genome-wide association studies (GWAS) as shared genetic risk factors for sCJD and the most common primary tauopathy, progressive supranuclear palsy (PSP)." (PMID 41186731, 2025).
hepatocellular carcinoma (4 papers, 2022 to 2025). A malignant tumor that arises from hepatocytes. "In hepatocellular carcinoma cells, STX6 has been reported to promote autophagy flux under nutrient repletion conditions likely by facilitating the association of autophagosomes with lysosomes." (PMID 40277356, 2025). "Then, we verified the carcinogenic effect of STX6 in hepatocellular carcinoma (HCC) and colorectal cancer (CRC) through a series of experiments in vitro and in vivo." (PMID 36612024, 2022).
Alzheimer disease (3 papers, 2024 to 2026). A progressive, neurodegenerative disease characterized by loss of function and death of nerve cells in several areas of the brain leading to loss of cognitive function such as memory and language. "Increased syntaxin-6 protein levels are also causally associated with Alzheimer's disease, suggesting it may have shared roles across multiple neurodegenerative diseases." (PMID 42017988, 2026).
tauopathy (3 papers, 2020 to 2026). Neurodegenerative disorders involving deposition of abnormal tau protein isoforms (tau proteins) in neurons and glial cells in the brain. "Taken together, this study functionally validates a role for syntaxin-6 in tauopathy pathogenesis, with syntaxin-6 knockout resulting in an early protective effect on multiple disease-relevant phenotypes in a humanised tauopathy model." (PMID 42017988, 2026). "To validate a role for syntaxin-6 in tauopathy pathogenesis, we knocked out syntaxin-6 in humanised P301S tauopathy mice." (PMID 42017988, 2026).
cognitive decline (2 papers, 2025). "Dysregulation of STX6 expression has been associated with AD risk and faster cognitive decline potentially relating to neuronal circuitry pathways." (PMID 39975316, 2025).
colon cancer (2 papers, 2018 to 2023). "Strikingly, we observed that while variations in copy number and DNAm of STX6 modulate expression differences between colon cancers, that the deregulation of STX6 expression between normal and cancer is clearly independent of copy-number and DNAm state." (PMID 29884221, 2018). "Western blot was performed on ten Golgi proteins (GBF1, GM130, Golgin97, TGN38, GRASP65, GRASP55, BLZF1, STX3, STX6, and GOLPH3) in small-cell lung cancer (SCLC), leukemia, colon cancer, and GIST cell lines expressing WT-KIT or MT-KIT." (PMID 37704840, 2023).
liver cancer (2 papers, 2022 to 2023). An epithelial or non-epithelial malignant neoplasm that arises from the liver. "Firstly, we only confirmed the connection between STX6 and cell-cycle progression and metastasis in liver cancer and colorectal cancer, leaving out the verification of other biological processes including apoptosis or drug resistance." (PMID 36612024, 2022). "In addition, we analyzed the mRNA levels of USF2 and STX6 in tumor tissues collected from patients with liver cancer and found that USF2 and STX6 expression levels were negatively correlated." (PMID 37564208, 2023). "With regard to STX6 protein levels, data from the CPTAC database indicate that STX6 was overexpressed in cancer tissues such as clear-cell RCC, UCEC, lung cancer, pancreatic cancer, head and neck cancer, and liver cancer, but not in GBM." (PMID 36612024, 2022).
renal cell carcinoma (2 papers, 2019 to 2024). "We first queried the TCGA-Renal Cell Carcinoma database for syntaxin 6 mRNA expression." (PMID 30816681, 2019). "Here, we examined the tumorogenic role of syntaxin 6 in renal cell carcinoma (RCC)." (PMID 30816681, 2019).
scrapie (2 papers, 2024 to 2025). A fatal disease of the nervous system in sheep and goats, characterized by pruritus, debility, and locomotor incoordination. "To explore whether syntaxin-6 plays a role in susceptibility to prion infection, we employed the scrapie cell assay (SCA), which is an ELISpot based method to quantify cell-associated prion infectivity." (PMID 41186731, 2025). "Infection of PK1 Stx6 knockdown cell lines with the mouse-adapted scrapie prion strain, RML, resulted in a statistically robust increase in the spot count, which was broadly consistent across split numbers and prion dilutions." (PMID 41186731, 2025).
Arrhythmia (1 paper, 2017). Any cardiac rhythm other than the normal sinus rhythm. "Second, our study suggested that the logistics molecules Stx6 is a direct target of miR-1 and participated in the process of miR-1-induced arrhythmia." (PMID 28397788, 2017). "Then, the question raised here is whether the intracellular Ca2+ contributes to the effect of Stx6 in arrhythmia." (PMID 28397788, 2017). "Thus, our studies reveals that trafficking-related gene Stx6 may regulate intracellular calcium and is involved in the occurrence of cardiac arrhythmia, which provides new insights in that miR-1 participates in arrhythmia by regulating the trafficking-related genes and pathway." (PMID 28397788, 2017).
atherosclerosis (1 paper, 2025). A disease characterized by the build-up of fatty material and calcium deposition in the arterial wall resulting in partial or complete occlusion of the arterial lumen. "Together, our findings highlight the miR-375-3p/STX6 axis as a critical regulator of endothelial cell senescence and a potential translational use in the prevention of atherosclerosis and related diseases." (PMID 41367311, 2025). "Mechanistically, the miR-375-3p/STX6 signaling axis promoted endothelial cell senescence via the SMAD2/p15 pathway in a SMAD2-dependent manner, and overexpression of STX6 attenuated atherosclerosis progression in mice." (PMID 41367311, 2025).
breast invasive carcinoma (1 paper, 2022). "Overall, cancers with STX6 mutations were predominantly amplified mutations, notably cholangiocarcinoma (>8%), liver hepatocellular carcinoma (>8%), and breast invasive carcinoma (>7%)." (PMID 36612024, 2022).
esophageal cancer (1 paper, 2022). A primary or metastatic malignant neoplasm involving the esophagus. "This is in line with findings of others demonstrating the involvement of syntaxin 1 in glioblastoma cell invasion, while expression of syntaxin 6 expression was associated with increased migration of esophageal cancer cell." (PMID 35668077, 2022).
Fanconi anemia (1 paper, 2023). Fanconi anemia (FA) is a hereditary DNA repair disorder characterized by progressive pancytopenia with bone marrow failure, variable congenital malformations and predisposition to develop hematological or solid tumors. "Among these 14 pathways, four major pathways were enriched: SNARE interactions involved in the vesicular transport (BET1 and STX6), leishmaniasis (FCGR1A, CYBB, and FOS), hematopoietic cell lineages (FCGR1A, ITGA3, MME, and CD5) and Fanconi anemia pathway (SLX4, ATR, and TELO2)." (PMID 37601105, 2023).
gastric cancer (1 paper, 2023). A primary or metastatic malignant neoplasm involving the stomach.
Insulin resistance (1 paper, 2014). Increased resistance towards insulin, that is, diminished effectiveness of insulin in reducing blood glucose levels. "We further show that insulin resistance can arise from defective GLUT4 sorting, and that ceramide disperses the GLUT4 and Stx6-positive compartment." (PMID 24705014, 2014).
ischemic heart disease (1 paper, 2017). "Then, we assumed that the defect of Stx6 contributes to ischemic heart disease by disturbing the intracellular Ca2+." (PMID 28397788, 2017).
myocardial infarction (1 paper, 2017). Gross necrosis of the myocardium, as a result of interruption of the blood supply to the area, as in coronary thrombosis. "Moreover, we found that Stx6 was decreased in the heart of mice after myocardial infarction and in the hypoxic cardiomyocytes, and further confirmed that Stx6 is a target of miR-1." (PMID 28397788, 2017).
ovarian carcinoma (1 paper, 2022). A malignant neoplasm originating from the surface ovarian epithelium. "Indeed, other members of the SNARE family, including syntaxin-6 and VAMP-4, colocalize with a P-type ATPase and induce the secretory vesicular transport of cisplatin, which in turn promotes cell growth in ovarian cancer." (PMID 35752613, 2022).
type II diabetes (1 paper, 2014). "For example, an up-regulation of STX6 mRNA 2 h post stimulation with LPS has been reported in RAW 264.7 macrophage cells and SNAP23 mRNA from the skeletal muscle of patients with type II diabetes was up-regulated." (PMID 25674084, 2014).
viral infection (1 paper, 2025). "This study employs proximity labeling to examine proteins near ACE2 post-viral infection and identified syntaxin-6 (STX6) as a factor that inhibits SARS-CoV-2 infection by impeding the endocytic release of the virus." (PMID 40277356, 2025). "Our study has demonstrated that viral infection induces a redistribution of endogenous STX6, shifting its primary perinuclear TGN location to a more punctate distribution in the cytosol." (PMID 40277356, 2025). "By conducting a comprehensive analysis of the proteomic changes in the vicinity of ACE2 during SARS-CoV-2 infection, we have identified STX6 as a key host restriction factor that impedes viral infection." (PMID 40277356, 2025). "Since STX6 was identified in the ACE2 proximity proteomic analysis shortly after viral infection, we initially assessed whether STX6 interacts with ACE2 or the spike protein and whether it colocalizes with viral particles shortly after entry." (PMID 40277356, 2025). "We report for the first time the function of STX6 as a restrictive factor in viral infection." (PMID 40277356, 2025). "Together, these findings support the hypothesis that STX6 is recruited to early endosomes in the aftermath of viral infection." (PMID 40277356, 2025).